C9orf72 (C9orf72-SMCR8 complex subunit)
Diseases named in the same sentence as C9orf72 in open-access papers (continued):
Sharing a sentence is not in itself a finding about the gene and the disease.
dementia (continued). "There is some evidence of genetic moderation of apathy in dementia, such as the apolipoprotein E gene (APOE) ε4 allele in Alzheimer's disease, as well as C9orf72 and GRN mutations in FTD." (PMID 33316852, 2021). "Examples of these cohorts are the GENetic Frontotemporal Dementia Initiative (GENFI; genotype data for GRN, MAPT, and C9ORF72 genes) and the Genetic and Environmental Risk in Alzheimer’s Disease (GERAD) Consortium (whole exome sequences)." (PMID 34559060, 2021). "Here, we evaluate BMAA exposure by investigating transcription signatures using PCR for dolphin genes homologous to those implicated in AD and related dementias: APP, PSEN1, PSEN2, MAPT, GRN, TARDBP, and C9orf72." (PMID 34678990, 2021). "Defects in nucleocytoplasmic transport in FTD point to important commonalities in the pathogenic mechanisms of tau-mediated dementias and ALS-FTD due to TDP-43 and C9orf72 mutations." (PMID 30650353, 2019). "In conclusion, this study represents the first genetic screening of C9orf72 repeat expansions in a Bulgarian dementia cohort." (PMID 30550541, 2018). "This study represents the first genetic screening for C9orf72 repeat expansions in a Bulgarian dementia cohort." (PMID 30550541, 2018). "The identification of a hexanucleotide repeat expansion in the C9orf72 gene as a frequent cause of both FTD and ALS suggests a possible role of this genetic alteration in other dementias or Parkinsonism-related movement disorders." (PMID 24803912, 2014). "In this study, we conducted a genome-wide DNA methylation (DNAm) analysis using EPIC version 2 (EPICv2) arrays on an FTD cohort comprising 27 carriers and 250 non-carriers of the pathogenic C9orf72 repeat expansion from the Amsterdam Dementia Cohort." (PMID 41024438, 2025). "The C9orf72 hexanucleotide repeat expansion is associated with ALS and certain forms of dementia, though its exact penetrance remains unclear." (PMID 40682810, 2025). "We spatially multiplexed the proteome geography at two levels of the cortex and the subcortical white matter in patients with various types of dementia (Alzheimer’s disease, C9orf72, MAPT also referred to as FTLD-tau, FTLD-TDP, FTLD-GRN; n = 6 per syndrome) and neurologically healthy controls (NHC)." (PMID 40476255, 2025). "Additionally, three studies reported associations in non‐AD dementias, namely, DLB and FTD patients with GRN, C9orf72 and MAPT mutations." (PMID 35338546, 2022). "In this work, we combined gene expression data for 16 772 genes from the Allen Institute for Brain Science atlas with brain maps of grey matter atrophy in symptomatic C9orf72, GRN and MAPT mutation carriers obtained from the Genetic Frontotemporal dementia Initiative study." (PMID 33210084, 2020). "Since cerebellar involvement in C9orf72 carriers have been found among FTD-ALS spectrum, it is conceivable that it may reflect a signature of ALS dementia other than a signature of the C9orf72 hexanucleotide repeat." (PMID 31133784, 2019). "We aimed to investigate mutation‐specific white matter (WM) integrity changes in presymptomatic and symptomatic mutation carriers of the C9orf72,MAPT, and GRN mutations by use of diffusion‐weighted imaging within the Genetic Frontotemporal dementia Initiative (GENFI) study." (PMID 30250860, 2018). "Moreover, most FLCN mutations isolated from BHD patients are loss of function leading to decreased protein stability or inability to interact with FNIP1/2, likewise the C9orf72 repeat expansion found in ALS and dementia cases results in a loss of function due to reduced C9orf72 protein expression." (PMID 38249578, 2023). "In the Genetic Frontotemporal Dementia Initiative (GENFI), only symptomatic GRN mutation carriers were found to have an increased global load of WMH when compared to normal controls, presymptomatic GRN mutation carriers, and both presymptomatic and symptomatic C9orf72 and MAPT mutation carriers." (PMID 34256835, 2021).
dementia (continued). "Fifteen C9orf72 HRE carriers [6.1% (2.3%–9.7%)] had recorded diagnoses of both ALS and dementia by age 80 compared to only one control [<0.1% (0%–<0.1%)]." (PMID 40682810, 2025). "Using this tool, we performed thalamus segmentations in MRI scans from C9orf72, GRN and MAPT mutation carriers and mutation non-carriers with suitable 3-Tesla MRI cross-sectional data from the GENetic Frontotemporal dementia Initiative." (PMID 41245435, 2025). "Accordingly, models exploring an interaction between C9orf72 HRE status and UNC13A genotype on risk indicated a potential interaction between genotypes for risk of any-cause dementia and ALS or any-cause dementia, but not ALS or FTD alone." (PMID 40682810, 2025). "First, we failed to perform screening of copy number variation (deletions or duplications) in the prion protein gene (PRNP), C9ORF72 (chromosome 9 open reading frame 72), and APP, which might be responsible for a proportion of EOAD and other types of dementia." (PMID 37051054, 2023). "We measured the complement proteins C1q and C3b in CSF by ELISAs in 224 presymptomatic and symptomatic GRN, C9orf72 or MAPT mutation carriers and non-carriers participating in the Genetic Frontotemporal Dementia Initiative (GENFI), a multicentre cohort study." (PMID 36064709, 2022). "We included 106 presymptomatic and 54 symptomatic carriers of a pathogenic mutation in GRN, C9orf72 or MAPT, and 70 healthy non-carriers participating in the Genetic Frontotemporal dementia Initiative (GENFI), all of whom had at least one CSF sample." (PMID 32273328, 2020). "In this specialized dementia clinic cohort, we found that 3.7% of all FTD cases (including the FTD-ALS patients) and 2.7% of all clinical AD cases had a C9orf72 repeat expansion, revealing a relatively low frequency of expanded repeats in the Bulgarian dementia cohort." (PMID 30550541, 2018). "A positive family history for FTD was present in one nfvPPA patient who had a hexanucleotide repeat expansion in chromosome 9 open-reading frame 72 (C9orf72) gene, and for AD in 2 lvPPA patients, whereas none of the svPPA patients had a clear autosomal dominant inheritance of any type of dementia." (PMID 34216263, 2022). "Moreover, the combination of calsyntenin-1 with other synaptic proteins has shown a potential ability to discriminate FTLD subtypes from other type of dementias, such as FTLD TDP-43-subtype from AD and healthy subjects, and GRN/C9orf72 pre-symptomatic mutation carriers from mutation non-carriers." (PMID 39000564, 2024). "To determine whether these differences begin prior to the onset of dementia, we compared the longitudinal rates of change of NPS among C9orf72+, GRN+, and noncarrier controls in the predementia phase." (PMID 40534487, 2025).
Parkinsonism (51 papers, 2012 to 2025). Characteristic neurologic anomaly resulting from degeneration of dopamine-generating cells in the substantia nigra, a region of the midbrain, characterized clinically by shaking, rigidity, slowness of movement and difficulty with walking and gait. "In this study, we investigated the pathogenesis of parkinsonism associated with striatal motor subdivisions in a pedigree with C9orf72 repeat expansions causing well-characterized FTDP by combining multiple imaging modalities." (PMID 36202819, 2022). "We believe our results provide a more comprehensive understanding of the mechanism of parkinsonism associated with the striatum in subjects with FTDP who have C9orf72 repeat expansions." (PMID 36202819, 2022). "Although, parkinsonism is a common clinical sign of C9orf72-associated diseases, described in over 75% affected people, sometimes Parkinsonism is a unique sign at onset, or it is only accompanied by ataxia or apraxia." (PMID 35754952, 2022). "GVD is also present in Down’s syndrome and primary tauopathies, as well as frontotemporal dementia cases with C9orf72 mutations and alpha synucleinopathies, such as Parkinson’s disease (PD), Lewy body dementia (LBD) and multiple system atrophy (MSA)." (PMID 33492460, 2021). "The C9orf72 expansion of a hexanucleotide GGGGCC repeat encoding dipeptide repeats exhibits variable phenotypic expressivity; individuals can develop MND and FTD (or both), and there are also associations between C9orf72 and parkinsonism, psychosis, and Huntington’s disease (HD) like phenotypes." (PMID 39501102, 2025). "We hypothesized that C9orf72 repeat expansions might cause impairment of the motor subregion in the striatum, which contributes to the manifestation of parkinsonism in FTDP." (PMID 36202819, 2022). "Recent work revealed that RQC is important for quality control of mitochondrial outer membrane-associated ribosomes, and that inefficiency of this process can compromise mitochondrial homeostasis and contribute to the pathogenesis of Parkinson’s disease and C9orf72-associated ALS/FTD." (PMID 34663454, 2021). "However, the underlying pathogenesis of parkinsonism in FTDP with C9orf72 repeat expansion remains unclear." (PMID 36202819, 2022). "The presence of atrophy, hypometabolism, and dopaminergic dysfunction, in the motor subregion of the striatum in FTDP may present a compelling argument in favor of parkinsonism owing to the involvement of motor subregions in the striatum associated with C9orf72 repeat expansions." (PMID 36202819, 2022). "The hexanucleotide repeat expansion in the C9orf72 gene is the most common cause of familial FTD, and parkinsonism has been reported in 25–35% of patients carrying the expansion." (PMID 35377014, 2022). "Akinetic–rigid parkinsonism, as far as TDP-43 proteinopathies are concerned, occurs commonly in PGRN mutations and is rather uncommon in C9orf72 mutations and VCP (Valosin Containing Protein) mutations and rare in TARDP mutations cases." (PMID 34943897, 2021). "It is well documented that the P301L MAPT mutation and C9orf72 repeat expansion were are predominantly associated with FTD in the western population, often accompanied by Parkinsonism." (PMID 34305575, 2021). "For this reason, in this review we focus on parkinsonism in genetic forms of ALS–FTSD with confirmed TDP-43 proteinopathy, caused by mutations in C9orf72, PGRN, and TARDBP." (PMID 34943897, 2021). "Examples are PICALM/CALM contributing to Alzheimer’s disease pathology, C9ORF72 implicated in ALS and FTD and several genes linked to Parkinson’s disease such as LRRK2, VPS35, SNCA, Synj1 and EndoA." (PMID 34988081, 2021). "Such aggregates are present in almost all cases of ALS, including SALS and FALS patients with pathogenic variants of C9ORF72, as well as in other neurodegenerative disorders, including FTD, Parkinson’s and Alzheimer’s disease." (PMID 33192262, 2020).
Parkinsonism (continued). "Noteworthy, c9orf72 repeat expansion display a high phenotypic variability, spanning from parkinsonism, to corticobasal degeneration, psychosis, and suicidal behavior." (PMID 30914912, 2019). "Studies have also linked C9orf72 to other clinical phenotypes outside of FTD and MND, including Parkinson’s disease, multiple system atrophy (MSA) and Alzheimer’s disease (AD), although many lacked neuropathological confirmation." (PMID 29704893, 2018). "Study of C9orf72 neuropathology has led to a suggestion as to why parkinsonism is more commonly seen in C9orf72 ALS cases." (PMID 25731823, 2015). "There is growing interest in intermediate repeat expansions in C9orf72 and their relationship to a wide range of neurological presentations, including Alzheimer’s disease, Parkinson’s disease, progressive supranuclear palsy, corticobasal degeneration, and corticobasal syndromes." (PMID 40138021, 2025). "In fact, it is well known that approximately 35% of C9orf72 patients have an atypical presentation mimicking other neurodegenerative disorders (Parkinson’s disease, Huntington’s disease, Lewy body dementia, Alzheimer’s disease, and parkinsonism) that can lead to misdiagnosis." (PMID 38356886, 2024). "In our previous study, we described the first Chinese FTDP family with C9orf72 repeat expansions, however, it is currently unclear whether C9ORF721 mutation carriers develop parkinsonism because of C9ORF721 causing involvement of the striatal motor regions." (PMID 36202819, 2022). "Up to 14–48% of the patients carrying the C9orf72 repeat expansion exhibit parkinsonism." (PMID 35377014, 2022). "Interestingly, parkinsonism was observed in more than 40% of FTD and FTD/ALS patients with pathogenic C9orf72 expansions." (PMID 34440384, 2021). "Notably, prominent parkinsonism was found for the first time in Chinese bvFTD patients with the P301L MAPT and C9orf72 gene mutation, respectively." (PMID 34305575, 2021). "However, only ~ 1 in 3 cases with C9orf72 mutation and 1 in 10 cases with PGRN mutations present with parkinsonism at onset." (PMID 34943897, 2021). "ETS-like tremor, parkinsonism, distal myoclonus, chorea with orofacial involvement, and cervical dystonia in the context of familial neurodegenerative conditions should prompt molecular genetic testing of the C9orf72 gene." (PMID 33977144, 2021). "To see if a similar phenomenon exists also for C9orf72 intermediate repeats, we analyzed Parkinson’s disease patients of Ashkenazi origin, in a stratified manner, in carriers of mutations in LRRK2, GBA, and/or SMPD1 genes, and in patients that do not carry these mutations." (PMID 34440384, 2021). "Since then, mutations in several other genes have been identified for FTLD with parkinsonism, including chromatin modifying protein 2B, chromosome 9 open reading frame 72 (C9ORF72), fused in sarcoma, valosin-containing protein, and transactive DNA-binding protein (TARDBP)." (PMID 29881367, 2018). "C9orf72 expansion was rare in the diagnosis of Parkinson’s Disease (PD)." (PMID 27400686, 2016). "Notably, autonomic dysfunction and ataxia might accompany the C9orf72-related parkinsonism, resembling MSA." (PMID 40722695, 2025). "In previous reports, parkinsonism and Richardson syndrome have been described in association with MAPT pathogenic variants,25, -, 27 but in our overall cohort, motor signs of a PSP-MP, PD-MP, and CBS-MP occurred most frequently in c9orf72 followed by GRN pathogenic variant carriers." (PMID 35948443, 2022). "Nevertheless, these results indicate that parkinsonism might be present in the pure FTDP phenotype with C9orf72 repeat expansion in China, thus suggesting that more attention should be paid to parkinsonism in patients with C9orf72 repeat expansion in clinical practice." (PMID 36202819, 2022).
Parkinsonism (continued). "However, as with our C9orf72 and sporadic ALS induced astrocytes, we found a consistent significant loss of GLO1 in the sporadic Parkinson’s disease cases compared to the sporadic Parkinson’s disease age and sex matched controls." (PMID 31647549, 2019). "The recent observations broaden the spectrum of clinical phenotypes associated with C9orf72 and suggest the existence of a novel C9orf72-positive ALS-parkinsonism (case 2) nosological entity that may be driven by an increased lesion load in extramotor areas, including the nigrostriatal system." (PMID 30550541, 2018). "Interestingly, none of our TIA1 mutation carriers developed significant parkinsonism or psychotic features, both of which are commonly reported in series with the C9orf72 mutation." (PMID 29216908, 2017). "The potential role of C9orf72 repeat expansions in other neurodegenerative disorders, such as Parkinson Disease (PD) or atypical parkinsonism is still to be elucidated." (PMID 27025851, 2016). "Given the overlapping of clinical phenotypes and pathological characteristics between these two diseases and Alzheimer's disease (AD), Parkinson's disease (PD), and essential tremor (ET), we speculated regarding whether C9orf72 repeat expansions also play a major role in these three diseases." (PMID 24068985, 2013). "The fact that motor disorders and parkinsonism are typically brought into connection with a MAPT pathogenic variant may be caused by the earlier discovery of MAPT pathogenic variants in people with PSP-like phenotypes, 8 years earlier than GRN6 and 13 years earlier than c9orf72." (PMID 35948443, 2022). "In this cohort, the C9orf72 pathological expansion was found in clinical diagnoses bridging the FTD, parkinsonism, ALS and AD spectrum." (PMID 30550541, 2018). "During the screening of C9orf72 in ALS cohorts, it was noted that there was also an apparent increase in the incidence of Parkinson’s disease (PD), parkinsonism concomitant with ALS or a family history of PD." (PMID 25731823, 2015). "In parallel with our findings, other recent studies have also shown an absence of an association between repeat expansion in the C9orf72 gene and disease susceptibility in AD, PD, or related Parkinsonism syndromes, especially in the Asian population." (PMID 24803912, 2014). "One example that parallels our findings for C9ORF72 is the major Parkinson disease gene LRRK2 that is broadly expressed in non-neuronal cells, and even within the nervous system, LRRK2 expression levels are low in the most affected area, the substantia nigra." (PMID 31612854, 2019). "Few research studies in FTDP patients with C9orf72 mutation have revealed the involvement of the striatum based on neuropathological and imaging analysis, however, it is ambiguous whether the pattern of striatum involvement is different between C9orf72-related FTDP and Parkinson’s disease." (PMID 36202819, 2022). "In a recent comprehensive review by Bourinaris and Houlden, C9orf72 intermediate repeat lengths were reported in several parkinsonism and movement disorders, including in Dopa-responsive PD, atypical parkinsonisms including PSP and MSA, essential-tremor plus parkinsonism, and spinocerebellar ataxia." (PMID 34440384, 2021). "The aim of this study was to analyze the hexanucleotide repeat numbers of C9orf72 gene in a mixed Taiwanese cohort with FTD, Parkinsonism syndrome, Parkinson’s disease (PD), and Alzheimer’s dementia (AD)." (PMID 24803912, 2014). "There were 587 altered proteins, regardless of C9ORF72-RE status and KEGG pathway analysis highlighted enrichment of inflammatory pathways, but also synaptic subtypes (glutamatergic and serotonergic) and several disease-associated pathways such as Parkinson’s disease and prion disease." (PMID 36309735, 2022).
Parkinsonism (continued). "Interestingly, GGGGCC repeat expansions in the C9orf72 gene was found in a family with FTD and Parkinsonism in the present study, thus suggesting that parkinsonism in affected individuals may be attributable to dopaminergic dysfunction of the putamen resulting from C9orf72 repeat expansion." (PMID 34305575, 2021). "Using immunohistochemistry we studied C9orf72 expression in the frontal cortex and the hippocampus of six Alzheimer's disease (AD) and 13 control cases, including ALS, Parkinson's disease, multiple system atrophy, and non-neurological cases." (PMID 22898310, 2012).